RAD51D (RAD51 paralog D)
Diseases named in the same sentence as RAD51D in open-access papers (continued):
Sharing a sentence is not in itself a finding about the gene and the disease.
ovarian carcinoma (continued). "Rare pathogenic mutations in RAD51 paralogs RAD51C and RAD51D have been identified in breast and ovarian cancer families and confer a high risk specifically for ovarian cancer whereas a homozygous missense mutation in RAD51C (FANCO) was found in a Fanconi anemia patient." (PMID 27149063, 2016). "In addition, RAD51C and RAD51D germline truncations are positively correlated with increased somatic mutation frequencies in ovarian cancer." (PMID 26689913, 2015). "Recent studies have conferred that the RAD51C and RAD51D genes, which code for the essential proteins involved in homologous recombination, are ovarian cancer (OC) susceptibility genes that may explain genetic risks in high-risk patients." (PMID 26057125, 2015). "Interestingly, there seems to be a higher prevalence of RAD51D mutations in families where there is elevated ovarian cancer burden (2 or more ovarian cancer cases)." (PMID 23586058, 2013). "RAD51D has subsequently been investigated in an additional series of 175 breast and ovarian cancer families, with an additional mutation being identified among the 51 families with at least two ovarian cancers (and among the 75 probands affected by ovarian cancer)." (PMID 23372765, 2013). "Indeed, RAD51C and RAD51D mutations have been specifically found in breast plus ovarian cancer families." (PMID 23300655, 2012). "The low yield in families having only one ovarian cancer may make gene-specific mutation testing of RAD51D impractical for the majority of ovarian/breast cancer families." (PMID 22415235, 2012). "In addition, it is well known that some HRR genes such as BRCA1/2, ATM, BRAD1, BRIP1, PALB2, RAD51C, and RAD51D are associated with high risk of ovarian cancers, and tissue detection might be a good way to learn the germline status." (PMID 35186721, 2022). "As studying French Canadians could facilitate the identification and interpretation of clinically relevant variants, we performed genetic analyses of RAD51C and RAD51D in this population comprised of cases with a family history of ovarian cancer or those who developed it at a young age." (PMID 35565380, 2022). "Interestingly, an additional mutation was detected in RAD51D, which may be associated with increased risk of breast cancer and is associated with increased risk of ovarian cancer." (PMID 28281021, 2017). "In consequence, a patient known to be a carrier could receive PARP inhibitors early in treatment, making clinical genetic testing of RAD51D mutations in BRCA1/2-negative patients with one or more familial ovarian cancers in the pedigree potentially highly beneficial." (PMID 22415235, 2012). "In our local high-risk Chinese breast and ovarian cancer cohort, RAD51C and RAD51D mutation percentages were 0.13% and 0.35%." (PMID 39202057, 2024). "RAD51C, RAD51D, BRIP1, and PALB2 are genes known to be associated with a hereditary risk of ovarian cancer." (PMID 39695768, 2024). "The study will enrol women, unaffected by cancer, undergoing predictive testing at a familial cancer clinic for a pathogenic variant in a known breast cancer (BC) or ovarian cancer (OC) predisposition gene (BRCA1, BRCA2, PALB2, CHEK2, ATM, RAD51C, RAD51D)." (PMID 39107016, 2024). "Studies on unselected breast or ovarian cancer cohorts in different populations showed that mutation frequencies of RAD51C and RAD51D in BC patients ranged from 0.07% to 0.2% and 0.07% to 0.48%, respectively." (PMID 39202057, 2024). "Pathogenic variants (PVs) in BRCA1, BRCA2, PALB2, RAD51C, RAD51D, and BRIP1 cancer susceptibility genes (CSGs) confer an increased ovarian cancer (OC) risk, with BRCA1, BRCA2, PALB2, RAD51C, and RAD51D PVs also conferring an elevated breast cancer (BC) risk." (PMID 38334999, 2024).
ovarian carcinoma (continued). "For ovarian cancer, management on RAD51C and RAD51D mutation carriers was also revised, with patients now being recommended for risk-reducing salpingo-oophorectomy (RRSO) at age 45–50, rather than just being considered for it." (PMID 39272924, 2024). "Discordancy was observed in 1 ovarian cancer case with a germline RAD51D PV, which showed borderline results for both genomic instability and RAD51 foci (GIS of 42 and 13% RAD51)." (PMID 38648056, 2024). "Next-generation sequencing (NGS) was conducted for the RAD51D genes in a 781 Chinese ovarian cancer patient cohort by the Chinese Academy of Medical Sciences and Peking Union Medical College, Beijing." (PMID 37833926, 2023). "Pathogenic variants in BRCA1/2 are also associated with ovarian cancer risk, as are pathogenic variants in PALB2, RAD51C, and RAD51D." (PMID 36765408, 2023). "BRIP1 is instead included on the corresponding gene panel for ovarian cancer predisposition, together with BRCA1, BRCA2, PALB2, RAD51C, RAD51D and the Lynch syndrome genes." (PMID 37563628, 2023). "For the 759 patients with a personal and/or familial history of only ovarian cancer, as expected, BRCA1/2 genes were the most frequently mutated, followed by RAD51C and RAD51D." (PMID 37444530, 2023). "Through modified segregation analysis including families from this study, risk estimates for breast and ovarian cancer have been refined for PTVs in RAD51C, RAD51D, PALB2 and for the moderate penetrance missense variant BRCA1 c." (PMID 37563628, 2023). "Along with defects in BRCA1 and BRCA2, other genes that function in homologous recombination repair (HRR) are mutated in ovarian cancer, albeit at lower frequencies, including RAD51C, RAD51D, BRIP1, PALB2, and ATM." (PMID 35223797, 2022). "New genes (RAD51C, RAD51D, and PALB2) have been identified as increasing susceptibility to ovarian cancer, but further research is required to investigate this." (PMID 35805770, 2022). "BRCA1 and BRCA2 were shown to be susceptibility genes for ovarian cancer, and the BRIP1, RAD51C, rad51D and mismatch repair genes also play a role in this disease." (PMID 35910206, 2022). "Ovarian cancers with germline or somatic mutation of BRCA1 or BRCA2, mutation of RAD51C or RAD51D, methylation of BRCA1, or high LOH have all been reported to respond to PARP inhibition." (PMID 35223797, 2022). "Next-generation sequencing (NGS) was conducted for the entire coding regions and exon/intron boundaries of the RAD51D genes in 781 Chinese ovarian cancer patients treated at our institution from January 1, 2015 to August 1, 2021." (PMID 36544182, 2022). "Other genes implicated in ovarian cancer, BRIP1, RAD51D, PALB2, and RAD51C, had a yield of 1.1% (n = 12), 0.8% (n = 9), 0.3% (n = 3), and 0.09% (n = 1), respectively." (PMID 35971132, 2022). "RAD51 paralogs (RAD51B, RAD51C, RAD51D, XRCC2, and XRCC3) have recently been involved in breast and ovarian cancer predisposition." (PMID 36544182, 2022). "The importance of the RAD51 paralogs was further underlined by genetic studies showing an increased risk of developing breast and/or ovarian cancer in women bearing RAD51C, RAD51D or XRCC2 mutations." (PMID 34208195, 2021). "In order to better characterize the clinical presentation of women with a PV in a moderate penetrance ovarian cancer-risk gene, we evaluated women with a PV in BRIP1, RAD51C, or RAD51D identified during hereditary cancer genetic testing." (PMID 33926482, 2021). "PVs in RAD51C and RAD51D were identified in 0.5% (149/27,915) and 0.3% (74/27,915) of women with ovarian cancer, respectively." (PMID 33926482, 2021). "In our cohort of 3422 index breast and ovarian cancer cases, we found RAD51B loss-of-function germline variants (9/3422 cases) to be almost as common as those affecting RAD51C and RAD51D (combined 16/3422 cases)." (PMID 34635660, 2021).
ovarian carcinoma (continued). "PVs in BRIP1, RAD51C, or RAD51D were identified in 0.5% of all tested women but in 1.6% of women with a history of ovarian cancer (~ 3-fold increase)." (PMID 33926482, 2021). "More recently, additional genes associated with increased ovarian cancer risk have been identified, including BRIP1, RAD51C, and RAD51D." (PMID 33926482, 2021). "In ovarian cancer, monoallelic RAD51C and RAD51D mutations are primarily germline, although somatic mutations have also been identified." (PMID 33015624, 2020). "Patients with pathogenic mutations in these RAD51 regulator genes, particularly RAD51C and RAD51D, have a higher risk of developing ovarian cancer [RAD51C, OR 8.3 (95% CI 5.43–12.48); RAD51D, OR 3.17 (95% CI 1.31–7.42)]." (PMID 33015624, 2020). "RAD51C and RAD51D are the most frequently mutated RAD51 paralogs in cancers and are most closely associated with increased ovarian cancer risk, although breast cancer risk is also increased." (PMID 33015624, 2020). "In this study, we aim to gain insight in the germline mutation spectrum of ATM, BARD1, BRIP1, ERCC4, PALB2, RAD51C and RAD51D in breast and ovarian cancer families from Spain." (PMID 32756499, 2020). "Among these 37 cases, 35 had breast cancer and 2 (ATM p.R805* and RAD51D p.K111fs) had ovarian cancer 13,15." (PMID 32566746, 2020). "The cumulative risk of having ovarian cancer by age 80 was estimated to be 11% (95% CI 6–21%) for RAD51C and 13% (95% CI 7–23%) for RAD51D based on their segregation analysis." (PMID 33086730, 2020). "RAD51 mutations have been identified in ovarian cancer; specifically, deleterious variants were shown in RAD51B, RAD51C, and RAD51D (nonsense, frameshift, and splice), with a predominance for RAD51C and RAD51D mutations." (PMID 31130614, 2019). "For example, S14 and S69 were associated with HBOC (not informative by BRCA testing) and harboured deleterious mutations in RAD51D and PALB2, which are moderate-risk genes for Ovarian Cancer (OC) and Breast Cancer (BC) respectively." (PMID 30675318, 2019). "Due to their role in BRCA1/BRCA2 DNA repair pathway, the loss-of-function mutations of RAD51C, RAD51D, BRIP1, and BARD1 genes have been generally considered as ovarian cancer susceptibility genes." (PMID 31366178, 2019). "Mutations in the human RAD51 paralogs (RAD51B, RAD51C, RAD51D, XRCC2, XRCC3, and SWSAP1) are found in a subset of breast and ovarian cancers." (PMID 30551670, 2018). "It has been estimated that 3% of hereditary ovarian cancer patients have a mutation in RAD51C, whereas 5% have a mutation in RAD51D." (PMID 30551670, 2018). "In this study, we have genotyped 68 MBC patients for the known breast or ovarian cancer associated mutations in the Finnish population in CHEK2, PALB2, RAD51C, RAD51D, and FANCM genes." (PMID 28874143, 2017). "In the Finnish population, recurrent founder mutations have been observed in many of the known breast and ovarian cancer susceptibility genes, including the RAD51 paralogs RAD51C and RAD51D." (PMID 27149063, 2016). "We have previously identified Finnish founder mutations in the ovarian cancer susceptibility genes RAD51C and RAD51D and recently, we identified a recurrent nonsense mutation in the FANCM gene that associated especially with triple-negative breast cancer." (PMID 25918678, 2015). "Current data from The Cancer Genome Atlas (TCGA) shows that the frequency of heterozygous loss of HELQ in ovarian cancer is comparable to RAD51C and RAD51D." (PMID 24005565, 2013). "The present study analysed the five RAD51 paralogs (RAD51B, RAD51C, RAD51D, XRCC2, XRCC3) to estimate their contribution to breast and ovarian cancer predisposition." (PMID 24139550, 2013).
ovarian carcinoma (continued). "Recent studies conducted on RAD51 paralogs, involved in the same DNA repair pathway, have identified rare germline mutations conferring breast and/or ovarian cancer predisposition in the RAD51C, RAD51D and XRCC2 genes." (PMID 24139550, 2013). "Mono-allelic germline mutations conferring breast and ovarian cancer predisposition were identified in RAD51C and RAD51D." (PMID 24139550, 2013). "While consensus was not reached for recontact of individuals with a GPV in intermediate penetrance CSGs (RAD51C and RAD51D) with respect to breast cancer risk management, consensus was reached for recontact for these genes (and BRIP1) with respect to ovarian cancer risk management." (PMID 41159931, 2025). "For RAD51D, 30.9% of women (21 of 68) had received a diagnosis of ovarian cancer." (PMID 38648056, 2024). "Our study differs from the research conducted by Manchanda et al31 on the cost-effectiveness of population-based testing for BRCA1, BRCA2, RAD51C (OMIM 602774), RAD51D (OMIM 602954), BRIP1 (OMIM 605882), and PALB2 mutations for preventing breast and ovarian cancer in the following ways." (PMID 38353949, 2024). "On the contrary, the personal and family history of the RAD51D carrier was negative for ovarian cancer, which is typically associated with this gene, and for breast cancer, except for one second-degree relative." (PMID 37239438, 2023). "Previous study showed that RAD51D mutation predispose to ovarian carcinoma but not to breast carcinoma in Caucasian women." (PMID 36544182, 2022). "The exact role of RAD51D in hereditary breast and ovarian cancer may be different in Chinese and Caucasian women." (PMID 36544182, 2022). "Currently, given the rarity of RAD51D mutations, the clinical characteristics and survival of RAD51D germline mutations carriers are not fully elucidated in Chinese ovarian cancer population." (PMID 36544182, 2022). "However, since the mutation spectrum of RAD51D was different in Chinese and Caucasian women, the exact role of RAD51D in hereditary breast and ovarian cancer should be further explored." (PMID 36544182, 2022). "In the BRIDGES project, the breast/ovarian cancer gene RAD51D has been sequenced in >113,000 women." (PMID 34200360, 2021). "Several studies performed in Western and Eastern countries showed evidence of moderate penetrance of ovarian cancer by germline RAD51D variants, regardless of ethnicity." (PMID 34838098, 2021). "Furthermore, the relative risk of ovarian cancer associated with RAD51C and RAD51D was comparable to BRCA2, with odds ratios for all three genes of approximately five." (PMID 33926482, 2021). "Women with mutations in moderate penetrance genes, such as RAD51C, RAD51D, and BRIP1 mutations, have a lifetime risk of 5.2–12% and may benefit from ovarian cancer screening." (PMID 32098383, 2020). "Loss-of-function variants in RAD51C and RAD51D increase the risk of breast and ovarian cancer, but the same has not been demonstrated for other RAD51 paralogs, or for RAD51 itself that plays a major role in HR repair." (PMID 33333735, 2020). "Therefore, RAD51C and RAD51D genes are included in several hereditary breast/ovarian cancer screening panels." (PMID 33015624, 2020). "Segregation analysis from large international consortia has been used to calculate ovarian cancer risks in RAD51C, RAD51D, and PALB2, and could be applied to other moderate risk ovarian cancer genes." (PMID 33086730, 2020). "Deletion of RAD51C and RAD51D alleles has been reported to moderately increase the lifetime ovarian cancer risk by 5–15%, but not RAD51B." (PMID 31366178, 2019).
ovarian carcinoma (continued). "Evidence was provided for the newer ovarian cancer-associated genes, such as RAD51C/RAD51D/BRIP1, which were associated with ovarian cancer risks of 5.8–11% and already met the requirement for risk-reducing salpingo-oophorectomy, which is recommended for patients with > 5% ovarian cancer risk." (PMID 31472684, 2019). "Population panel testing for BRCA1/BRCA2/RAD51C/RAD51D/BRIP1/PALB2 gene mutations is the most cost-effective genetic-testing strategy in general-population women and can prevent thousands more breast and ovarian cancers than current clinical-criteria based approaches." (PMID 30400647, 2018). "Mutations in RAD51C and RAD51D are rare and have been primarily linked to an increased risk for ovarian cancer rather than breast cancer alone." (PMID 28874143, 2017). "The associations are even stronger when only specific-cancer genes are considered: all specific-cancer genes in the DSBR class are associated with estrogen-related tissues (CHEK2, breast cancer; RAD51C and RAD51D, ovary cancer; and the DSBR cancer gene BRCA1, breast and ovary)." (PMID 26856619, 2016). "For model development, genetic data will involve genetic testing of high penetrance genes associated with hereditary breast and ovarian cancer, BRCA1 and BRCA2, as well as lower penetrance genes associated with ovarian cancer susceptibility, BRIP1, RAD51C and RAD51D." (PMID 25391615, 2015). "Two overtly deleterious RAD51D mutations were identified among the unselected ovarian cancers cases (0.82%) but none were detected among the 1,060 families." (PMID 23372765, 2013). "The identification of a series of genes that are involved in the BRCA-FA DNA repair pathway inspired more systematic searches for other pathway components, which resulted in the discovery of two further prominent ovarian cancer risk genes in 2011 and 2012: RAD51C and RAD51D." (PMID 23344037, 2013). "More recently, RAD51D was found to be associated with ovarian cancer, but not breast cancer, with an estimated relative risk of 6.3." (PMID 23344037, 2013). "Hereditary ovarian cancer is probably underestimated, since recent studies highlight new susceptibility genes (RAD51C, RAD51D, PALB2) that might predispose for ovarian cancer, but their exact prevalence is still under investigation." (PMID 23536787, 2013). "Recent data show that mutations in RAD51D have an aetiological role in ovarian carcinoma, yet mutations do not appear to be associated with an increased risk for breast cancer." (PMID 22415235, 2012). "RAD51D should be included in genetic screening of ovarian cancer families that do not have BRCA1/BRCA2 mutations." (PMID 22415235, 2012). "In Japan, the proportion of germline variants in ovarian cancer is approximately 18%, and the major genes are BRCA1, BRCA2, mismatch repair genes [MutL protein homolog (MLH) 1, MLH2, MLH6, and postmeiotic segregation increased 2], RAD51 Paralog D, and ataxia telangiectasia mutated (ATM)." (PMID 39807103, 2025). "The small number of PALB2 mutations limits interpretation; however, RAD51C, RAD51D, and BRIP1 mutations were associated with both high rates of biallelic loss and high GIS, suggesting that these genes might be true drivers of HRD in ovarian cancer." (PMID 39695768, 2024). "Finally, germline mutations in Breast Cancer Gene 1 (BRCA1), Breast Cancer Gene 2 (BRCA2), BRCA1 interacting Protein 1 (BRP1), Partner and Localizer of BRCA2 (PALB2), RAD51 homolog C (RAD51C), RAD51 homolog D (RAD51D), and individuals with Lynch syndrome are susceptible to ovarian cancers." (PMID 37110218, 2023). "Consistently, a retrospective case-control analysis of ovarian cancer patients enrolled in the ARIEL2 and ARIEL3 trials suggested an increased incidence of tMN among patients carrying pathogenic variants in genes involved in homologous recombination pathway (BRCA1, BRCA2, RAD51C and RAD51D)." (PMID 37119509, 2023). "RAD51D may play more important role in Chinese hereditary breast and ovarian cancer patients." (PMID 36544182, 2022).